PITPNB (phosphatidylinositol transfer protein beta)
Description:
Catalyzes the transfer of phosphatidylinositol and phosphatidylcholine between membranes. Also catalyzes the transfer of sphingomyelin (By similarity). Required for COPI-mediated retrograde transport from the Golgi to the endoplasmic reticulum; phosphatidylinositol and phosphatidylcholine transfer activity is essential for this function.
Synonyms: PI-TP-beta; VIB1B; PtdInsTP
Tractability: PROTAC: ubiquitination databases record sites on it; its protein half-life has been measured.
Gene: Protein-coding gene on chromosome 22 (27,851,669 to 27,920,134, reverse strand). Ensembl gene ENSG00000180957.
Subcellular location: Cytoplasm, cytosol; Golgi apparatus membrane; Endoplasmic reticulum membrane; Golgi apparatus
Subcellular location (Human Protein Atlas): Cytosol; Vesicles
Pathways (Reactome):
Metabolism: PI and PC transport between ER and Golgi membranes
Gene Ontology:
Molecular function: phosphatidylcholine binding; phosphatidylcholine transfer activity; phosphatidylcholine transporter activity; phosphatidylinositol binding; phosphatidylinositol transfer activity; phospholipid transfer activity; protein binding; sphingomyelin transfer activity; quaternary ammonium group binding
Biological process: phospholipid transport; retrograde vesicle-mediated transport, Golgi to endoplasmic reticulum; lipid metabolic process; nucleus organization; intermembrane lipid transfer; lipid translocation
Cellular component: cytoplasm; cytosol; endoplasmic reticulum membrane; Golgi apparatus; Golgi membrane
Genetic constraint (gnomAD): Loss-of-function variants: 1 observed, 1.68 expected, observed/expected ratio (o/e) 0.6, 90% interval 0.19 to 1.81. That is too few expected variants to judge how well the gene tolerates losing a copy. Missense variants: 4 observed, 14.3 expected, observed/expected ratio (o/e) 0.28, 90% interval 0.14 to 0.64. Synonymous variants: 8 observed, 6.32 expected, observed/expected ratio (o/e) 1.27, 90% interval 0.72 to 1.88.
Homologues: Orthologues: chimpanzee PITPNB (98% identical), macaque PITPNB (98% identical), dog PITPNB (97% identical), mouse Pitpnb (96% identical), rabbit PITPNB (96% identical), guinea pig PITPNB (94% identical), pig PITPNB (89% identical), rat Pitpnb (88% identical), zebrafish pitpnb (83% identical), tropical clawed frog pitpnb.2 (73% identical). Paralogues in human: PITPNA (77% identical), PITPNM2 (46% identical), PITPNM1 (46% identical), PITPNC1 (37% identical), PITPNM3 (7% identical).
Diseases named in the same sentence as PITPNB in open-access papers:
PITPNB is named in the same sentence as 6 diseases in open-access papers, as found by Europe PMC text mining. Sharing a sentence is not in itself a finding about the gene and the disease. The quoted sentences say what the papers report.
breast carcinoma (1 paper, 2026). "Pathway enrichment revealed associations with cell cycle regulation (E2F3, MKI67), DNA repair (BRCA2), and transcriptional control (MED1), with six priority genes (MED1, BRCA2, E2F3, PITPNB, H1-1, and FARP2) showing established breast cancer relevance." (PMID 41614924, 2026).
Burkitt lymphoma (1 paper, 2024). A rare form of malignant mature B-cell non-Hodgkin lymphoma. "In the EBV‐positive Burkitt's lymphoma cell line Raji, treated with 5 μM 5E2‐12 and 10 μM S10, we assessed EBNA1 binding at various sites, including EBV dyad symmetry (DS) and the EBV Qp, and a cellular binding site at the PITPNB gene." (PMID 39399647, 2024).
Moyamoya disease (1 paper, 2025). Moyamoya disease (MMD) is a rare intracranial arteriopathy involving progressive stenosis of the cerebral vasculature located at the base of the brain causing transient ischemic attacks or strokes. "PITPNB may precisely play a synergistic role with other potential pathogenic genes of Moyamoya disease in lipid metabolism, jointly regulating the metabolism in Moyamoya disease." (PMID 40722175, 2025).
PITPNB also shares sentences with these, for which no sentence is quoted: infection (1 paper); meningioma (1); myeloid leukemia (1).